TGFB1 (transforming growth factor beta 1)
Diseases named in the same sentence as TGFB1 in open-access papers (continued):
Sharing a sentence is not in itself a finding about the gene and the disease.
tumor (continued). "In fact, TGFβ1 is pathologically upregulated in humans as a result of tumor cell proliferation, can be secreted by tumor cells, and is a negative predictor of DFS and OS." (PMID 34768810, 2021). "The results of single-cell mRNA sequencing show PMEPA1 were mainly expressed in basal tumor cells and CAFs, TGFB1 were mainly expressed in basal tumor cells, CAFs and TAMs, PTGS2 were hardly expressed in those cells." (PMID 34777336, 2021). "In the current study, we also found that the level of TGFβ1 in CAFs was associated with the prognosis of patients with SCLC, and tumor cell progression, multivariate analyses indicated that TGFβ1 was an independent indicator for prognosis in all cohorts." (PMID 34095135, 2021). "Staining for CADM3, IGLON5, and TGFB1 was low in tumor tissue; staining for LEP and ABI3BP was medium in tumor tissue; staining for CD1B was high in tumor tissue." (PMID 34497681, 2021). "Then, we screened possible factors associated with poor outcomes, including having tumours, a chronic onset and factors associated with relapses, which included having lower levels of CSF BAFF and a larger ratio of serum TGFβ1/serum CXCL13." (PMID 34872566, 2021). "This overexpression of TGFB1 by tumour cells modulates epithelial-mesenchymal transition, impairs immune surveillance and promotes angiogenesis, therefore promoting tumour invasion and metastasis." (PMID 33761981, 2021). "TGFβ1 suppressed tumor development by regulating the cell cycle, via increasing levels of cyclin-dependent kinase inhibitors (e.g., p15InK4b and p21Waf1/Cip1) and reducing c-Myc." (PMID 34095135, 2021). "In our model of established B16 tumors, PD-L1 expression significantly increased on tumor-infiltrating CD11b+ and CD11c+ cells as a result of TGFβ1 and TGFβ3 isoform-specific and pan-TGFβ inhibition." (PMID 34789823, 2021). "While anti-PD-1 treatment alone effectively controlled B16 tumor growth in comparison to TGFβ monotherapy; the combination of anti-TGFβ1 with anti-PD-1 therapy was superior to either treatment alone in delaying tumor growth." (PMID 34789823, 2021). "Through CGGA and TCGA transcriptome analysis, we found that the expression of MXRA5 was highly positively correlated with the expression of immune checkpoints, the immunosuppressive factor TGFB1, and tumor invasion markers." (PMID 34211612, 2021). "The current study found that differences in TGFβ1 levels in CAFs appeared to affect the tumor immune microenvironment." (PMID 34095135, 2021). "High levels of TGFβ1 were positively associated with PD-L1, CD206, and FoxP3 levels in tumor tissues, but inversely with that of CD8, CD56, and CD86." (PMID 34095135, 2021). "TGFB1 has been recognized as the most predominant immune-suppressing molecular by inducing Treg cells infiltration into tumor microenvironment and by inhibiting the generation, differentiation and function of effector T cells." (PMID 33854592, 2021). "Anti-TGFβ3 therapy resulted in the greatest delay in tumor growth (62.3% reduction in tumor size compared to control), followed by anti-TGFβ1 therapy (49.68%) and pan-TGFβ blockade (37.44%) calculated 24 days post tumor implantation." (PMID 34789823, 2021). "We did not observe any significant changes in the levels of secreted TGFβ1 when Arl4c was knocked down in the cancer cells themselves, further confirming that this effect of Arl4c on promoting tumor stemness and drug resistance depends on its role in PSCs." (PMID 34849465, 2021). "In the tumor microenvironment, CAFs interact with other cells through direct cell-to-cell contact and by secreting cytokines such as TGFβ1, epidermal growth factor (EGF), hepatocyte growth factor (HGF), and interleukin 6 (IL-6)." (PMID 34095135, 2021). "TGFβ1 signaling cross-talking with hedgehog signaling has been previously reported in tumorigenesis and tumor metastasis." (PMID 33430164, 2021).
tumor (continued). "Both, IL1β and TGFβ1, along with some more soluble factors, have been described to be molecules that mediate the crosstalk between tumor cells and fibroblasts and are responsible for the activation state of the latter." (PMID 34066976, 2021). "The protein levels of TGFβ1 secreted from cells and expressed in tumor tissues of tumor bearing mice were both detected by ELSIA and IHC, and the expression of TGFBR1 was detected by western blot." (PMID 34249724, 2021). "Mechanistically, we found that TGFβ1 regulates tumor progression via tumor microenvironment reprogramming rather than by inducing EMT." (PMID 33608500, 2021). "In particular, we found increased relative expression of MMP1, COL6A1, COL6A3, and TGFB1 in MCTS relative to tumor spheroids." (PMID 34035369, 2021). "Dexamethasone offered inhibitory activity against hypoxia and TGFβ1-induced EMT of tumor cells by blocking the expression of transcription factors such as Snail1, Slug, and Twist." (PMID 34220337, 2021). "Recently, studies indicated that TGFβ1 greatly participated in numerous immune regulatory functions, such as tumor immune suppression and escape." (PMID 33995472, 2021). "We performed similar analysis for two other genes known to be relevant to tumor grade in CRC: the tight junction-associated protein ZO-1/TJP1, and a regulator of epithelial-mesenchymal transition, TGFβ1." (PMID 34237057, 2021). "We also found downregulation of the expression of TGFB1, a critical molecule involved in cell invasion and tumor metastasis, in HIPK2-OE cells." (PMID 33613771, 2021). "Platelets also increase tumor cell metastatic potential by activating the TGFb-1 and NF-kB pathways, which are responsible for the EMT." (PMID 34926234, 2021). "As cytokines function as a critical role in the regulation of tumor immunity, we investigated the expression of two immunosuppressive cytokines including IL-10 and TGFB1." (PMID 34960256, 2021). "TGFB1 has both stimulatory and inhibitory roles in cancer progression; it acts as a tumour suppressor at the early stage of cancer development and promotes invasion and metastasis at the later stage of cancer progression." (PMID 33761981, 2021). "Here, we explored oncogenes regulated by TGFβ1 that are also involved in signaling pathways and interactions within the tumor microenvironment." (PMID 34218518, 2021). "Next, we prospectively isolated the CD90+CD73+ mesenchymal cell subset from both LUAD and LUSC tumour digests and exposed them to the pleiotropic cytokine TGFβ1." (PMID 34740105, 2021). "TIMER platform analysis indicated CHI3L2 expression was closely related to diverse marker genes of tumor immune infiltrating cells, including monocytes, TAMs, M1 macrophages, M2 macrophages, TGFβ1+ Treg and T cell exhaustion in GBM and LGG." (PMID 33937022, 2021). "As a major proximal cytokine within tumours, transforming growth factor beta 1 (TGFβ1) decreases cytotoxicity of neutrophil and mediates polarization of N2 neutrophils from N1 type." (PMID 34841706, 2021). "A few small tumor nodules were observed in c-Myc/TGFβ1 livers at 11.6 weeks post injection, and several larger individual tumor lesions were detected by 18 weeks post injection." (PMID 33608500, 2021). "Nonetheless, in contrast to the high number of HCC lesions in the c-Myc HCC model, tumor number in c-Myc/TGFβ1 mice was extremely low." (PMID 33608500, 2021). "The CAFs isolated from the patient tumor specimens were judged as TGFβ1-high or TGFβ1-low, i.e., higher or lower than the median for 34.3." (PMID 34095135, 2021). "During tumor metastasis, TGFβ1-stimulated CAFs secreted IL-11 to enhance the survival of CRC cells and increased the efficiency of organ colonization." (PMID 34735373, 2021). "Cortisol, an adrenal hormone, was more robustly produced in the male liver and contributed to the increased production of tgfβ1, which has been mentioned earlier to possess pro-tumour functions in tumorigenesis." (PMID 34680297, 2021).
tumor (continued). "Cancer-associated fibroblasts (CAFs), a protective barrier of the tumor, activate metabolically reprogrammed TAMs and block T-cell penetration into tumor nests by secreting transforming growth factor beta 1 (TGF-β1)." (PMID 35096565, 2021). "This study concluded that high POSTN levels in the tumour microenvironment resulting from the POSTN/TGFβ1 positive feedback loop can activate AP-2α to transcriptionally induce the expression of CD133, which promotes the stemness transformation of HCC cells." (PMID 34193219, 2021). "We found that TGFβ1 was significantly expressed in the 11q‐deleted tumor, thus probably contributing to tumor immune escape in these patients." (PMID 33252831, 2021). "Its expression can be deregulated by its soluble ligands and by growth factors such as TGFβ1, secreted by the tumor as an evasion mechanism to prevent its recognition and immune destruction." (PMID 33671415, 2021). "By administering doxycycline with the food, TGFβ1 expression is induced in the mouse HCC, thus allowing the investigation of TGFβ1 role in tumor progression." (PMID 33608500, 2021). "Concerning the mechanisms supporting lymphatic invasion, α6β4 integrin-expressing macrophages in TBNCs adhere to BM laminin 5 of the lymphovasculature and release TGFβ1, thus eliciting RhoA-dependent lymphatic EC contraction that favors tumor intravasation." (PMID 34131655, 2021). "In CT26 the predominant isoform expressed by infiltrating immune cells is TGFβ1 and correspondingly anti-TGFβ1 demonstrated superior tumor control." (PMID 34789823, 2021). "And the expression analysis showed the PMEPA1 was mainly expressed in tumor cells and CAFs, TGFB1 was expressed in all three cells, and most of the chemokines were highly expressed in TAMs." (PMID 34777336, 2021). "In contrast, a TGFβ1-dependent cell cycle arrest at the G1 phase has been described in both normal epithelium and tumor tissue, potentially supporting a role in tumor suppression." (PMID 34830768, 2021). "In B16 there is an equal expression of both isoforms on infiltrating immune cells and isoform-specific inhibition of either TGFβ1 or TGFβ3 curbed tumor growth." (PMID 34789823, 2021). "A study where ECD cleavage was induced in lung epithelium tumor cells pretreated either with oncostatin M alone or combined with TGFβ1 generated fragments with a higher affinity for HA than cells pretreated only with TGFβ1." (PMID 33505471, 2021). "Constance J. Martin’s paper notes that the selective inhibition of TGFB1 can change the tumor immune landscape and improve tumor tissue resistance to ICI therapy." (PMID 34220801, 2021). "The activation of fibroblasts into CAFs with a myofibroblastic phenotype is heavily driven by TGFβ1 and leads to the development of many pro-tumor desmoplastic features seen in PDAC." (PMID 33589694, 2021). "Altogether, the present data indicate a crucial contribution of TGFβ1 related tumor microenvironment reprogramming in modulating c-Myc HCC progression." (PMID 33608500, 2021). "The TGF-β family includes three closely related molecules, TGFβ1, 2 and 3 whose roles in maintaining immune homeostasis are crucial, but which also play a complex role in tumour development." (PMID 35069536, 2021). "Since we found that both TGFβ1 and TGFβ3 isoform expression were detectable at 11 days post tumor implantation, a time point at which the B16F10 tumors are palpable and well established, we began treatment with isoform-specific anti-TGFβ therapy at this time." (PMID 34789823, 2021). "In the early stages of tumourigenesis, TGFB1 acts as a tumour suppressor, through inhibition of cell proliferation, induction of apoptosis and suppression of growth factor, cytokine and chemokine production." (PMID 33761981, 2021). "Activation of αvβ3 prompts TGFβ1 to be released into the tumour microenvironment in its active form." (PMID 34193219, 2021).
tumor (continued). "Abnormalities involving the TGFB1 gene and its receptors are common in several types of cancer and often related to tumor progression." (PMID 33905626, 2021). "TGFβ1 is reported to be a versatile cytokine involved in cancer cell metastasis, drug resistance, and tumor fibrosis." (PMID 34849465, 2021). "It is worth to note that tumor lesions, although with a longer latency, still developed in c-Myc/TGFβ1 injected mice." (PMID 33608500, 2021). "While weakly positive IR for TGFB1 was observed throughout the tumor mass, a marked increase in TGFB1 IR was noted at the leading edge of tumors." (PMID 34131649, 2021). "Elevated TGFβ1 levels were observed in the primary tumor and in plasma from CRC patients and were correlated with metastasis and poor prognosis." (PMID 34975867, 2021). "Immunohistochemical staining was used to determine the expression levels of RUNX1, ARP2/3, TSP1, and TGFβ1 in tumor sections, which we found lower levels of their expression in RUNX1-knockdown specimens than their control counterparts." (PMID 34376784, 2021). "TGFB1, which was mainly secreted by CAFs and TAMs, was one of the main inducements of tumor immunosuppressive microenvironment." (PMID 34055889, 2021). "The cancer cell survival suppressive effect of dipyridamole was paralleled by a reduction of the HMGB1/RAGE axis, and proliferation- and migration-related β-catenin, YAP1, Runx2, TGFβ1/Smad, and cyclin D1 in in vitro and in vivo tumor growth models." (PMID 33669632, 2021). "At day 15 post tumor implantation, TGFβ1 and TGFβ3 are highly expressed on CD8+DCs and Ly6G+ granulocytes." (PMID 34789823, 2021). "The complexity of the effects of TGFβ1 in tumor stroma on tumor cells and the mechanisms involved require further elucidation." (PMID 34095135, 2021). "TGFB1 is a polypeptide member of the transforming growth factor-beta (TGFB) superfamily, a cytokine that predominantly exists in the tumor microenvironment." (PMID 34307149, 2021). "First, in a model of SOX4 upregulation via TGFβ-1, since this cytokine is produced in higher levels in MM, by both tumor cells and BMSCs, exerts inhibitory effects on normal B-cell proliferation and Ig secretion, and regulates the secretion IL-6 in MM cells." (PMID 34945712, 2021). "In particular, TGFβ1 has been shown to be involved in regulating tumor proliferation, epithelial-to-mesenchymal transition (EMT), and tumor microenvironment during HCC progression and metastasis." (PMID 33608500, 2021). "In contrast, overexpression of TGFβ1 enhanced c-Myc HCC progression by promoting tumor cell metastasis." (PMID 33608500, 2021). "Among the 10 survival-related genes included in the signature, the risk-associated genes PWP2 and TGFB1 have been suggested to be associated with GC invasion and metastasis, and ZBTB7A, a protection-associated gene, plays a tumor-suppressive role in GC cells." (PMID 34413861, 2021). "Together, these data suggest that palladin plays a central role in the production of d-ECMs that sustain tumor cell proliferation while exogenous TGFβ1 induced ECM alignment is dispensable for this role." (PMID 33589694, 2021). "To further investigate the function of PMEPA1 in BLCA, we evaluated the correlation between PMEPA1 and TGFB1, chemokines, and immune checkpoints in tumor cells, CAFs, and TAMs." (PMID 34777336, 2021). "As tumours progress, tumour cells can express abundant TGFB1 which appears to have largely pro-tumorigenic effects." (PMID 33761981, 2021). "When TGFB1 signaling is inhibited in the mammary gland, mice exhibit shorter tumor latency and increased tumor incidence." (PMID 34771552, 2021). "Another study showed that HER2-targeted drug resistance is correlated with an increased amount of transforming growth factor beta 1 (TGF-β1) and programmed death-ligand 1 (PD-L1) and resistance to the anti-tumor immune response." (PMID 33800302, 2021).
tumor (continued). "POSTN formed a positive feedback loop with TGFβ1 to induce and maintain its high expression in the tumour microenvironment." (PMID 34193219, 2021). "Second, an indirect way through normalizing the tumor microenvironment, capmatinib-osimertinib combination regimen resulted in the reduced TGFβ1 secretion, which promotes CAF transformation, by the osimertinib-resistant NSCLC." (PMID 33621951, 2021). "Since TGFβ signaling is known to play both tumor suppressor and protumorigenic roles dependent on the cancer type and stage, we analyzed contributions of MIR100HG and TGFB1 to overall survival of patients with different tumors." (PMID 33941855, 2021). "Previous studies have indicated that SLC members were regulated by TGFβ1, and a bispecific antibody of TGF-β and PD-L1 showed a potent and durable antitumor activity by normalizing tumor immune microenvironment and enhanced anti-tumor immune response." (PMID 34977043, 2021). "Next, to delineate the role of TGFβ1 signaling in modulating the progression, especially metastasis, of c-Myc induced mouse HCCs in vivo, we employed the intrasplenic injection tumor model." (PMID 33608500, 2021). "The synergistic effect of TGFβ1 and platelet activating factor promotes tumor metastasis and induces the EMT process of tumor cell." (PMID 34764993, 2021). "Our previous research revealed that Sulf2 can stimulate the expression and secretion of POSTN through TGFβ1 in the HCC tumour microenvironment." (PMID 34193219, 2021). "These sprouting neovasculatures not only promote the exit of dormant cancer cells but also accelerate tumor growth by secreting TGFβ1 and periostin, which are tumor-promoting factors." (PMID 34208521, 2021). "TGFβ1 acts as a tumor suppressor, by inhibiting cell proliferation and promoting apoptosis of tumor cells." (PMID 34095135, 2021). "In the context of cancer, TGFβ1 can act both as a tumor suppressor, in the early stages of cancer, and as a tumor promoter, in the later stages of tumor progression." (PMID 34868988, 2021). "We observed increased expression of 5 immune suppressive genes including PVR (CD155), TGFB1, NT5E (CD73), VEGFA, and CD276 (B7-H3) in 9p21-loss tumors across multiple tumor types/subtypes when compared to 9p21-WT tumors." (PMID 34556668, 2021). "The results show PMEPA1 were mainly expressed in basal tumor cells, CAFs, endothelial cells, muscle cells, and urothelial cells, TGFB1 were mainly expressed in basal tumor cells, CAFs, and TAMs, PTGS2 were hardly expressed in those cells." (PMID 34777336, 2021). "They show that RUNX1 is necessary for driving blood vessel co-option from surrounding liver tissue and that regulation of this process relies on a signaling feedback loop between RUNX1 transcriptional target TSP1 in tumor cells and TGFβ1 in the liver." (PMID 34376784, 2021). "Together with our findings, it appears that non-lymphoid cells, in particular myeloid cells, are critical sources of TGFβ1 and TGFβ3 across different tumor types." (PMID 34789823, 2021). "Studies have shown that TGFβ1 can promote the expression of VEGF in tumor cells through autocrine or paracrine modes and then affect tumor angiogenesis." (PMID 34778094, 2021). "hBMMSCs also increased tumor progression, but decreased pulmonary metastasis with decreased TGFβ1 levels in HCC." (PMID 33849537, 2021). "In the end, we revealed a hitherto unappreciated role of autocrine TGFβ1 in the control of cell motility that is not only compatible with the proposed role of RAC1B as a tumor suppressor but even provides strong evidence in favor of it." (PMID 33260366, 2020). "The application of TGFβ1 can partially reverse this trend and reduce tumor proliferation and MVD in vivo." (PMID 33193874, 2020). "All of these exhibited a 4-fold enrichment over the tumor cells, but only Tgfb1 was statistically significant (p-value = 0.0076)." (PMID 32290096, 2020).